LPIN1 (lipin 1)
Diseases named in the same sentence as LPIN1 in open-access papers (continued):
Sharing a sentence is not in itself a finding about the gene and the disease.
lipodystrophy (continued). "Spontaneous loss-of-function mutations in the gene encoding Lipin-1 have been identified in the fatty liver dystrophic (FLD) mice, characterized by a massive liver steatosis in the pre-suckling period and a severe lipodystrophy associated with glucose intolerance in adult animals." (PMID 35250856, 2022). "Despite the absence of obvious signs of adipose tissue loss and lack of the metabolic disturbances usually associated with lipodystrophy, we cannot yet exclude that human lipin-1-defective individuals (as in rodents) manifest some failures of adipose tissue homeostasis." (PMID 28986436, 2017). "To investigate the consequences of the deficiency of lipin-1 in human adipogenesis, we examined fat biopsies from human patients carrying biallelic inactivating mutations in the LPIN1 gene, to search for signs of defects in the histological structure indicative of lipodystrophy." (PMID 28986436, 2017). "It now appears likely that both of these lipin isoforms may influence adipogenesis, perhaps explaining why loss of lipin 1 alone does not cause overt lipodystrophy in humans." (PMID 25737955, 2015). "The fact that humans with lipin-1 deficiency do not manifest lipodystrophy suggests that a compensatory mechanism for TAG synthesis could exist in human adipose tissue." (PMID 26176221, 2015). "No clinically significant lipodystrophy was observed in patients with a lipin 1 defect, and this was not due to compensation by lipin 2 or lipin 3, indicating the existence of alternative pathways that are important for TAG synthesis in human adipocytes." (PMID 37964368, 2023). "However, WAT in lipin-1-defective human individuals develops without detectable histopathological signs of lipodystrophy and with an apparently normal qualitative composition of stored lipids." (PMID 28986436, 2017). "BSCL2, PTRF and LPIN1 lipodystrophy genes are not differentially expressed." (PMID 26176221, 2015). "HIV patients on cART regimens who are affected by metabolic syndrome and lipodystrophy have decreased lipin-1 mRNA expression in subcutaneous adipose tissue, compared to HIV-infected patients without metabolic complications and lipodystrophy." (PMID 31133852, 2019). "Interestingly, Lipin-1, the enzyme that catalyses the transformation of PA into diacylglycerol (DAG) has been involved in lipodystrophy in mice only, not in human." (PMID 35250856, 2022).
metabolic syndrome (13 papers, 2013 to 2025). A cluster of metabolic risk factors for CARDIOVASCULAR DISEASES and TYPE 2 DIABETES MELLITUS. "The allele T of rs13412852 in LPIN1 is associated with lower body mass index and insulin levels, thus it is possibly considered as a protector for the metabolic syndrome alterations." (PMID 30986988, 2019). "The mRNA expression of LPIN1 in liver and adipose tissue have positive associations with body mass and insulin sensitivity, and its polymorphisms have been associated with metabolic syndrome." (PMID 30986988, 2019). "In humans and mice, Lpin-1 is associated with metabolic syndrome and type 2 diabetes and mutations in human LPIN2 cause Majeed syndrome." (PMID 23496871, 2013). "Deleterious mutations in Lpin1 can cause fatty liver dystrophy and various dyslipidemias in mice." (PMID 31617323, 2019). "Abnormal LPIN1 is associated with metabolic syndromes, vacuole regulation, and diabetes." (PMID 31665133, 2019). "LPIN1 is also a known susceptibility gene for metabolic syndrome and type 2 diabetes." (PMID 30065651, 2018). "LPIN1 SNPs and haplotypes that may confer variability in the protein activity have been associated with several components of the metabolic syndrome, including body mass, insulin levels, resting metabolic rate and to responsiveness to insulin sensitizers." (PMID 23394097, 2013). "However, in a recent meta-analysis conducted in 8504 subjects the LPIN1 rs13412852 T allele was associated with lower BMI and insulin levels, confirming that it possibly represents a protective factor towards metabolic syndrome alterations." (PMID 23394097, 2013). "Moreover, Ppard interaction with hepatic AMPK (phospho-AMP-activated protein kinase), PGC-1α (PPARα-PPARγ coactivator), and lipin-1 refers to them as therapeutic targets in the prevention of dyslipidemia." (PMID 24799886, 2014).
breast carcinoma (11 papers, 2015 to 2025). "In this study, we demonstrated for the first time that the IL-33/ST2 signaling pathway plays an important role in regulating LPIN1 expression, by enhancing the association of the c-Jun transcription factor with the LPIN1 promoter in breast cancer cells." (PMID 33946554, 2021). "In this study, we demonstrate the tumour intrinsic effect of lipin-1 in causing breast cancer malignancy through promoting lipid synthesis." (PMID 33203880, 2020). "These clinical associations demonstrate that the Src-mediated lipin-1 tyrosine phosphorylation is highly correlated with human breast cancer malignancy and poorer prognosis." (PMID 33203880, 2020). "Furthermore, the proto-oncogene Src mediates LPIN1 phosphorylation on tyrosine residues, which is strongly associated with malignancy and poor prognosis in breast cancer." (PMID 40002245, 2025). "LPIN1 overexpression has been observed in an increasing number of cancers including breast cancer, high‐grade prostate cancer, and lung adenocarcinoma." (PMID 40265168, 2025). "It has been shown that the expression of LPIN1 is significantly elevated in breast cancer tissues compared with normal breast tissues, and lipid synthesis regulated by LPIN1 promotes BCC migration." (PMID 40256431, 2025). "A reduction of LPIN1 expression decreased the migration of prostate cancer cells via the activation of RhoA and also decreased the migration of breast cancer cells." (PMID 40265168, 2025). "It was found that the expression of LPIN1 messenger RNA was significantly elevated in breast cancer tissues, and when it was inhibited, BCC migration was reduced, suggesting a promoting effect of LPIN1-regulated lipid synthesis on BCC migration." (PMID 40256431, 2025). "Phosphorylated lipin-1, which enhances adipogenesis in breast cancer, is positively correlated with tumor size, lymph node metastasis, time to recurrence, and patient survival." (PMID 39333940, 2024). "More importantly, we found that COT-JNK1/2 is a pivotal signaling transducer for the regulation of LPIN1 expression in breast cancer cells." (PMID 33946554, 2021). "We found that IL-33 levels were positively correlated with LPIN1 levels in breast cancer tissues, indicating that the IL-33 facilitates breast carcinogenesis via enhanced LPIN1 expression." (PMID 33946554, 2021). "They demonstrated also that the c-src-lipin-1 axis and the phosphorylation of lipin-1 on tyrosine 795 are essential in breast cancer cells for their proliferation in vitro, and for the formation of tumors in vivo." (PMID 33922580, 2021). "We observed that COT-JNK is a critical signal transducer for the regulation of LPIN1 expression by IL-33 induction in breast cancer cells." (PMID 33946554, 2021). "In the present study, we showed that the IL-33-induced COT-JNK1/2 signaling pathway regulates LPIN1 mRNA and protein expression by recruiting c-Jun to the LPIN1 promoter in breast cancer cells." (PMID 33946554, 2021). "Previous studies also demonstrated that the Lipin-1 knockdown repressed proliferation of prostate and breast cancer cells." (PMID 33596934, 2021). "The high expression of LPIN1 has been shown in various cancers, including breast cancer and prostate cancer, and its overexpression correlates with poor prognosis in these patients." (PMID 33946554, 2021). "In contrast, five of the nine IL-33-high samples also had higher expression of LPIN1, indicating a positive correlation of IL-33 with LPIN1 levels in human breast cancer." (PMID 33946554, 2021).
breast carcinoma (continued). "Several studies have reported that LPIN1 is upregulated in several cancers, including breast cancer and prostate cancer, and its expression levels are positively correlated with the poor prognosis of triple-negative breast cancer and lung adenocarcinoma." (PMID 33946554, 2021). "Along with the development of breast cancer, levels of Tyr-phosphorylated lipin-1 were increased in mammary tumours from the transgenic mice, congruent with elevated levels of the activated p-Tyr416-Src." (PMID 33203880, 2020). "Here the authors show that proto-oncogene Src interacts and phosphorylates metabolic enzyme phosphatidic acid phosphatase LPIN1 (lipin-1) to promote growth and metastasis in breast cancer." (PMID 33203880, 2020). "Given that the PyVT tumour model is known to mimic the Luminal B type breast cancer, we also tested the role of lipin-1 in different subtypes of breast cancer patient-derived xenografts (PDXs)." (PMID 33203880, 2020). "The specific inhibition of lipin-1 in prostate and breast cancer cells demonstrates its critical importance for cell proliferation and migration through deregulation of several intracellular signaling pathways." (PMID 25834103, 2015). "SRC, an oncogene, interacts with LPIN1 and promotes breast cancer development." (PMID 40256431, 2025). "Treatment with propranolol also reduced an IL-33-mediated increase in the number of MCF-7 cell colonies in the soft agar assay, indicating that LPIN1 induced by the COT/JNK1/2 pathway is essential for anchorage-independent proliferation of breast cancer under IL-33 stimulation." (PMID 33946554, 2021). "In the present study, we demonstrated that the IL-33/ST2/COT/JNK1/2 signaling pathway could overexpress LPIN1 in breast cancer cells." (PMID 33946554, 2021). "Similarly, the Cancer Genome Atlas (TCGA) data showed that IL-33 and LPIN1 expression levels were positively correlated in the breast cancer patients." (PMID 33946554, 2021). "Among eleven breast cancer samples with low IL-33, ten samples also showed lower LPIN1 expression." (PMID 33946554, 2021). "Moreover, unphosphorylable lipin-1 is unable to promote growth and metastasis of breast cancer spontaneously developed in PyVT;Lpin1−/− mice in vivo." (PMID 33203880, 2020). "Since our data demonstrated that lipin-1 silencing sensitizes prostate and breast cancer cells to rapamycin, we then verified whether pharmacological inhibition of lipins activity could be considered as a potential therapeutic option or not." (PMID 25834103, 2015). "Additionally, evidence has emerged indicating that IL-33 might influence breast cancer metabolism, especially by elevating Lipin-1 (LPIN-1) expression, a molecule involved in phospholipid metabolism." (PMID 37762328, 2023). "Consequently, the overexpression of enzymes involved in triglyceride synthesis, e.g., GPAT2, LPIN1, and DGAT, is a common alteration in breast cancer." (PMID 40002245, 2025). "A correlation with cancer aggressiveness was also confirmed in models showing that lipin-1 silencing increases autophagy, and strongly represses prostate and breast cancer cell proliferation and migration without affecting normal cells." (PMID 33922580, 2021). "Furthermore, propranolol and SP600125, which are LPIN1 and JNK1/2 inhibitors, respectively, strongly suppressed IL-33-induced colony formation in breast cancer cells and mammary gland tumor development." (PMID 33946554, 2021). "We next isolated and engineered PyVT;Lpin1−/− mice-derived spontaneous mammary tumour cells with or without lentivirus-mediated re-expression of WT-lipin-1 or 3YF-lipin-1." (PMID 33203880, 2020). "To study for whether lipin-1 would affect the spontaneous development of mammary tumour, we crossed the MMTV-PyVT transgenic mice with Lpin1+/− mice, generating PyVT;Lpin1−/− mice." (PMID 33203880, 2020). "Re-expression of 3YF-lipin-1 in PyVT;Lpin1−/− mice fails to promote progression and metastasis of mammary tumours." (PMID 33203880, 2020).
breast carcinoma (continued). "The proliferation of prostate and breast cancer cells, but not of non-tumorigenic cells, was repressed upon lipin-1 knock-down." (PMID 25834103, 2015).
steatosis (11 papers, 2007 to 2025). Increased lipid within the cytoplasm of cells. "Resultantly, the circRNA_021412/miR-1972/LPIN1 signaling uncovered an important mechanism that underlay the transcription-dependent role of circRNA in metabolic regulation and steatosis induction." (PMID 28717649, 2017). "Collectively, the data demonstrated that myeloid cell-specific lipin-1 deficiency ameliorated liver damaged but slightly exacerbated steatosis in mice after ethanol administration." (PMID 27666676, 2016). "In such a way, Kit loss-of-function mimicked the downregulation of Lpin1, Lpl and Vldlr leading to juvenile steatosis and growth retardation." (PMID 17612398, 2007). "Alteration in CCR7, IMPDH2, IL6ST, MYC, LPIN1, PDE7A and RORA was significantly associated with hepatotoxicity including liver damage, -hyperplasia, -inflammation, -steatosis, -fibrosis, -necrosis and -proliferation." (PMID 26907258, 2016). "The increased expression of LPIN1 in patients with steatosis, together with the fatty acid-induced translocation of LPIN1 to the endoplasmic reticulum, facilitates increased triacylglycerol synthesis." (PMID 22969728, 2012). "Consequently, reactivated miR-1972 induces reductions in the transcriptional and/or translational levels of LPIN1, thereby inducing the expression of steatosis-related genes via the activation of the PPARα." (PMID 40941416, 2025). "Consequently, reactivated miR-1972 decreases the transcriptional and/or translational levels of LPIN1, inducing steatosis-related gene expression via PPARα." (PMID 40941416, 2025). "Further than the PNPLA3 and the TM6SF2 SNPs, we therefore tested the rs3750861 KLF6, the rs13412852 LPIN1, and the rs4880 SOD2 SNPs, which have demonstrated associations with fibrosis, steatosis and fibrosis, and again fibrosis, respectively, in previous studies on NAFLD patients." (PMID 29732362, 2018). "Indeed, 8 steatosis-related genes of the metabolic pathways were recognized to be transcriptionally induced by LPIN1 in our experiments." (PMID 28717649, 2017). "Therefore, downregulation of Lpin1 in Kit mutants will lead to a reduced oxidation of lipids and steatosis in a context of increased lipid delivery during suckling." (PMID 17612398, 2007). "Surprisingly, deletion of lipin-1 in myeloid cells dramatically attenuated liver inflammatory responses and ameliorated liver injury that would normally occur following the ethanol feeding protocol, but slightly exacerbated the ethanol-induced steatosis in mice." (PMID 27666676, 2016). "Second, direct interaction between LPIN1 and transcription factors (PPARα, PGC-1α) amplifies the hepatic PGC-1α/PPARα signaling in steatosis-related gene expression." (PMID 28717649, 2017). "Thus, reactivated miR-1972 downregulated the lipin 1 (LPIN1) level, and this was followed by induction of the expressions of steatosis-related genes via PPARα activation." (PMID 35162956, 2022). "We demonstrated that ablation of myeloid cell-specific lipin-1 selectively ameliorated hepatic inflammation but not steatosis in mice after ethanol administration." (PMID 27666676, 2016).
diabetes (7 papers, 2015 to 2025). "In their study, the genes GCKR, KCNJ11, and TCF7 were associated with hypertriglyceridemia and diabetes, while the LPIN1 and SLC22A1 genes were linked to a favorable response to antidiabetic drugs like rosiglitazone and metformin." (PMID 39408795, 2024). "Lipin 2 mRNA is also induced in liver by fasting and diabetes, but lipin 1 and lipin 2 are under the control of different regulatory pathways." (PMID 33003344, 2020). "Although lipin 2 is more abundant than lipin 1 in normal mouse liver, hepatic lipin 1 expression is highly induced by fasting, diabetes, glucocorticoid administration, and experimental alcoholic fatty liver disease." (PMID 33003344, 2020). "Interestingly, polymorphisms in the LPIN1 and LPIN2 genes are associated with traits of metabolic disease, including insulin sensitivity, diabetes and increased blood pressure, as well as the response to thiazolidinediones." (PMID 26232096, 2015). "Concerning the potential role of LPIN1 rs13412852, KLF6 rs3750861, SOD2 rs4880, TM6SF2 rs58542926, and ZNF624 rs12603226 SNPs in glycemic control of the patients with diabetes, data are also limited." (PMID 34746177, 2021). "The increased expression of lipin-1 together with the fatty acid-induced translocation of lipin-1 and lipin-2 to the ER facilitates increased TAG synthesis in starvation, diabetes, and stress conditions." (PMID 30934807, 2019).
hepatoma (6 papers, 2011 to 2023). "Reduced levels of RBM4, as seen in fasted Lpin1–/– liver, are associated with poor prognosis in hepatocellular carcinoma following hepatectomy." (PMID 34494556, 2021). "For example, Dgat2 can affect the progression of hepatocellular carcinoma by regulating the cell cycle, and overexpression of Lpin1 can promote the proliferation and migration of ovarian cancer cells." (PMID 35122680, 2022). "Lipin 1 was fused to the BirA* biotin ligase and expressed in Hepa1-6 mouse hepatoma cells." (PMID 34494556, 2021). "Knockdown of SIRT3 in human hepatoma cells confirmed the upregulation in both HIF-1α and LIPIN 1 protein levels, whereas this increase was blunted when cells were exposed to palmitate." (PMID 32912335, 2020). "When human hepatoma cell line HepG2 cells were treated with taurocholic acid (TCA), the lipin-2 protein level decreased, while the lipin-1 protein was not changed under the same conditions." (PMID 21857965, 2011).